AREG (amphiregulin)
Diseases named in the same sentence as AREG in open-access papers (continued):
Sharing a sentence is not in itself a finding about the gene and the disease.
colon carcinoma (29 papers, 1999 to 2025). "This markedly elevates the mRNA levels of NR4A2, COX2, and the regulatory proteins AREG and IL-6, thereby facilitating the development of sporadic or colitis-associated colon cancer." (PMID 39683442, 2024). "We conclude that specific iron compounds affect cell signaling differently and some may increase the risk of colon cancer advancement in an amphiregulin-dependent fashion." (PMID 29682205, 2018). "For example, left-half colon cancer has high expression of epiregulin (EREG) and amphiregulin (AREG) proteins, while right-half colon cancer has high mutation rates of the TGFbR2 and BRAF genes." (PMID 41182556, 2025). "AREG, coding for amphiregulin, a member of the epidermal growth factor family, is reportedly overexpressed in colon cancer and activates both MAP kinase and PI3K/Akt canonical signaling in tumor cells." (PMID 32971867, 2020). "In breast and colon cancer, cancer-derived exosomes containing amphiregulin, an epidermal growth factor receptor ligand, have been implicated in cellular signaling and increased invasiveness." (PMID 28796150, 2017). "Further, PGE2 has been reported to promote AREG induction and to stimulate growth of colon cancer cells." (PMID 28415726, 2017). "In line with our observation, EGF was demonstrated to induce morphological changes in colon cancer cell lines whereas AREG had an effect only on cell proliferation." (PMID 27643613, 2016). "In support of this possibility there is work showing a role for stromal myofibroblast production of amphiregulin and epiregulin in promoting colon tumor growth in the setting of inflamed human colon." (PMID 23805328, 2013). "Indeed, AREG was shown to induce a potent proliferative response in colon carcinoma cells and an increased proliferation in airway epithelial and smooth muscle cells." (PMID 35841013, 2022). "Overall, our data indicate that colon cancer-associated ADAM17 variants (E319G, E406X, M435I) exhibit diminished substrate recognition and/or enzymatic activity towards physiological substrates of the metalloprotease (TNFα, IL-6R, AREG)." (PMID 33143292, 2020). "However, increased expression levels of AREG and EPR in tumors of colon cancer patients are associated with cetuximab sensitivity." (PMID 20856931, 2010). "Furthermore, elevated AREG expression associates with tumor budding, invasion, poor prognosis, and increased sensitivity to EGFR inhibition in HNSCC, while TGFα can confer cetuximab resistance through inducing EGFR-MET interaction in colon cancer." (PMID 41115375, 2025). "In colon cancer, PGE2 and EGF, products formed by the cyclooxygenase (COX-2) pathway, have been shown to induce amphiregulin production." (PMID 29682205, 2018). "As MAPK and PI3K play a central role in transduction of signals from EGFR, and the activation of Ras/Raf/MAPK pathway induces AREG transcription in colon cancer cells, we examined if EGF induce AREG through these pathways." (PMID 27669890, 2016). "Similarly, in colon cancer, overexpression of FGFR4 triggers AREG secretion, which promotes tumor growth through EGFR phosphorylation at Tyr1068." (PMID 39451251, 2024). "Another exomere protein amphiregulin (AREG) could serve as the EGFR ligand, regulate the EGFR signaling pathway in normal intestinal organoids, and significantly promote the growth of colonic cancer organoids." (PMID 33791224, 2021). "In patient P0009, a quadruple negative colon cancer case, both epiregulin and amphiregulin exhibited extraordinary over-expression based on RNA-Seq data analysis, making a case for cetuximab treatment." (PMID 27245685, 2016).
colon carcinoma (continued). "The upreguation of TAGLN and downregulation of SOX9, IRS1, P15, AREG, IER5L, KRT8 in RKO, SW620 and CW2 colon cancer cells indicated these genes may be the target molecules for the biological behaviour of IGFBP-rP1 in colon cancer." (PMID 20977730, 2010). "We found that IGFBP-rP1 could upreguate TAGLN, downregulate SOX9, IRS1, P15, AREG, IER5L, KRT8 in these colon cancer cells, indicating that these genes may be the important IGFBP-rP1 responsible genes in colon cancer." (PMID 20977730, 2010). "Thus, TORC1 activation might be an important molecular mechanism mediating the effects of PGE2 on colon tumor growth, inducing pro‐tumorigenic transcription of genes including NR4A2, COX2, AREG, and IL‐6." (PMID 35920319, 2023). "Furthermore, EGFR-stimulation induces COX-2 and PGE2 production in OSCC cell lines, which may further increase AREG expression due to EGFR-cross activation, as shown for colon cancer cell lines." (PMID 27669890, 2016).
ovarian carcinoma (28 papers, 2015 to 2025). A malignant neoplasm originating from the surface ovarian epithelium. "AREG hinders anti-tumor immunity, which is associated with stemness and chemoresistance in ovarian cancer." (PMID 40510161, 2025). "While it has been previously reported that AREG is overexpressed in ovarian cancer and is associated with advanced stage disease, using bioinformatic analyses we failed to observe an association between AREG expression and patient survival." (PMID 38831884, 2024). "Amphiregulin, is a well-studied protein, which has been found to be associated with the ovarian function and apoptosis of epithelial cells in ovarian cancer." (PMID 27258020, 2016). "Specifically, ADAM17 increases its activity when ovarian cancer cells are treated with cisplatin, leading to amphiregulin (AREG) shedding and subsequent EGFR signaling." (PMID 41050403, 2025). "Previous studies have shown that AREG is crucial for ovarian cancer cell proliferation and metastasis in mice co-injected with CAFs and ovarian cancer cells." (PMID 39451251, 2024). "TCGA ovarian cancer cohort analysis revealed that AREG mRNA levels were significantly (p = 0.007) upregulated in patients defined as having a chemoresistant versus sensitive platinum status." (PMID 38831884, 2024). "According to studies investigating both hepatocellular and melanoma carcinoma, AREG plays a crucial role in cell invasion and metastasis, and AREG promotes ovarian cancer stem cells and drug resistance through the AREG-EGFR-ERK pathway." (PMID 37604948, 2023). "AREG‐neutralising antibody remarkably inhibited ovarian cancer growth and enhanced chemotherapy efficacy." (PMID 36639835, 2023). "It has been reported that miRNA-34c-5p represses amphiregulin-stimulated ovarian cancer drug resistance and stemness by downregulating the AREG/EGFR/ERK axis." (PMID 35342412, 2022). "Even though the EGF ligands Nectin-4, HB-EGF and AREG have been described as rational targets for blood-based detection of ovarian cancer, their application as biomarkers for early-stage ovarian cancer so far has not been shown." (PMID 36497350, 2022). "SPRY2 acts as tumor suppressor in BrCa by inhibiting the Ras/Mitogen-Activated Protein Kinase Pathway, and in ovarian cancer, through inhibition of Amphiregulin (AREG)-induced cell invasion." (PMID 32005108, 2020). "AREG was chosen as ADAM17 substrate because it was previously identified as one of the most abundant ADAM17 substrates in advanced ovarian cancer." (PMID 29662625, 2018). "One study using an antibody against AREG in ovarian cancer xenografts has successfully reduced tumor growth." (PMID 30367629, 2018). "In conclusion this report highlights the relevance of ADAM17 and AREG in ovarian cancer, and possibly opens up new directions to overcome platinum resistance in ovarian cancer treatment." (PMID 29662625, 2018). "Upon cisplatin treatment of the ovarian cancer cell lines Igrov-1 and A2780, we identified both, an enhanced AREG release as well as an increased AREG mRNA and protein expression in cell lysates." (PMID 29662625, 2018). "A neutralizing AREG antibody (AR30) e.g. revealed synergistic effects with cisplatin on the growth of human ovarian cancer xenografts." (PMID 29662625, 2018). "We further explored the correlation of AREG expression level and clinical outcomes of ovarian cancer patients." (PMID 28459431, 2017). "Overexpression of AREG was found to be correlated with advanced ovarian cancer stages and poor prognosis." (PMID 28459431, 2017). "Our data also demonstrated that miR-34c-5p was able to repress ovarian cancer stemness and drug resistance via targeting AREG-mediated EGFR-ERK pathway." (PMID 28459431, 2017). "Our investigation for the first time demonstrated that AREG was upregulated in ovarian cancer stem-like cells and contributed to ovarian cancer stemness characteristics." (PMID 28459431, 2017).
ovarian carcinoma (continued). "We also first revealed that miR-34c-5p directly targeted AREG and downregulated AREG-mediated ovarian cancer stemness and drug resistance." (PMID 28459431, 2017). "Higher IHC score of AREG protein expression correlated with the advanced stages of ovarian cancer in both clinical patients and the tissue array samples." (PMID 28459431, 2017). "This confirms that the AREG-EGFR-ERK pathway is upregulated in ovarian cancer stem-like cells and implies that AREG regulates ovarian cancer stemness and drug resistance through the AREG-EGFR-ERK pathway." (PMID 28459431, 2017). "In the present study, we successfully enriched ovarian cancer stem-like cells and for the first time demonstrated the essential role of AREG in regulating ovarian cancer stemness." (PMID 28459431, 2017). "In survival study, Kaplan–Meier survival analysis of 518 cases from the Oncomine data showed that ovarian cancer patients with high AREG expression correlated with a significantly shorter survival than those with low AREG expression (P=0.0003)." (PMID 28459431, 2017). "Altered expression levels of AREG and miR-34c-5p were found in those ovarian cancer stem-like cells." (PMID 28459431, 2017). "It is concluded that miR-34c-5p inhibits AREG-augmented ovarian cancer stemness and drug resistance through downregulation of the AREG-EGFR-ERK pathway." (PMID 28459431, 2017). "The effects of AREG and miR-34c-5p on ovarian cancer stemness and drug resistance were investigated for the first time." (PMID 28459431, 2017). "In this study, we demonstrated that miR-34c-5p directly targeted and downregulated AREG to inhibit ovarian cancer stemness and drug resistance." (PMID 28459431, 2017). "Taken together, our data suggest that AREG promotes ovarian cancer stemness and drug resistance via the AREG-EGFR-ERK pathway and this is inhibited by miR-34c-5p." (PMID 28459431, 2017). "We further demonstrated that miR-34c-5p inhibited ovarian cancer stemness through downregulation of the AREG-EGFR-ERK pathway." (PMID 28459431, 2017). "Our study has demonstrated that AREG has an important role in promoting ovarian cancer stemness and drug resistance." (PMID 28459431, 2017). "We are also the first to identify that miR-34c-5p inhibits ovarian cancer stemness and drug resistance through downregulation of the AREG-EGFR-ERK pathway." (PMID 28459431, 2017). "AREG treatment similarly up-regulated SPRY2 expression in another human ovarian cancer cell line, OVCAR5." (PMID 27835572, 2016). "To investigate AREG expression and its relationship with ovarian cancer patient survival, we queried mRNA expression data on 489 high-grade serous ovarian carcinomas samples that were published by the Cancer Genome Atlas (TCGA) Research Network." (PMID 27835572, 2016). "Furthermore, AREG-neutralizing antibodies have been shown to inhibit tumor growth and metastasis in ovarian cancer models." (PMID 40725192, 2025). "Our analysis of publicly available datasets revealed AREG’s upregulation in chemoresistant ovarian cancer patients, further strengthening our previous observation of AREG’s significant upregulation in HGSOC patient tumors following exposure to frontline carboplatin and paclitaxel." (PMID 38831884, 2024). "Therefore, in the present study, we evaluate the ADAM17 substrates Nectin-4, HB-EGF and AREG as a potential blood-based detection method for ovarian cancer." (PMID 36497350, 2022). "It has been previously reported that AREG overexpression leads to enhanced cell proliferation, migration, invasion, cancer stemness, and drug resistance in ovarian cancer, further supporting the idea that chemotherapy results in the upregulation of genes with pro-tumorigenic implications." (PMID 36131935, 2022).
ovarian carcinoma (continued). "For both breast and ovarian carcinomas, it has been shown that the increased release of various substrates such as AREG, transforming growth factor alpha (TGF-alpha), and HB-EGF activates the EGFR receptor and contributes to tumorigenesis and disease progression." (PMID 36497350, 2022). "The aim of this study is to investigate whether the ADAM17 substrates Nectin-4, Heparin-binding EGF-like growth factor (HB-EGF) and Amphiregulin (AREG) could function as potential tumor markers for ovarian cancer." (PMID 36497350, 2022). "In the present study, we successfully enriched ovarian cancer stem-like cells and demonstrated that AREG promotes ovarian cancer stemness and drug resistance via the AREG-EGFR-ERK pathway and that miR-34c-5p targets AREG to inhibit ovarian cancer stemness and drug resistance." (PMID 28459431, 2017). "Both AREG and miR-34c-5p could potentially serve as prognostic biomarkers and/or targets for developing ovarian cancer therapeutics." (PMID 28459431, 2017). "In conclusion, our data implies that miR-34c-5p could be a promising strategy in the treatment of ovarian cancer via downregulation of the AREG-EGFR-ERK pathway to inhibit ovarian cancer stemness and drug resistance." (PMID 28459431, 2017). "The results suggest that the expression of AREG in ovarian cancer patients correlates with poor clinical outcomes and could serve as an important prognostic marker." (PMID 28459431, 2017). "Targeting AREG, miR-34c-5p could be a potential strategy for anti-cancer-stem cell therapy in ovarian cancer." (PMID 28459431, 2017). "Taken together, these results suggest that targeting AREG is a potential new clinical approach that could lower the overall mortality and morbidity of human ovarian cancer." (PMID 27835572, 2016). "Moreover, AREG has been reported to regulate ovarian cancer progression in an autocrine/paracrine manner." (PMID 27835572, 2016). "In addition, the current study and our previous studies show that AREG can stimulate ovarian cancer cell invasion by down-regulating E-cadherin expression." (PMID 27835572, 2016). "Indeed, a recent study demonstrates that shRNA-mediated AREG depletion or treatment with an anti-AREG monoclonal antibody inhibits the growth of human ovarian cancer cells." (PMID 27835572, 2016). "Finally, we observed that the DEGs DUSP5 (r = 0.487, p < 0.0001), CXCL2 (r = 0.355, p < 0.0001), and IL-6 (r = 0.401, p < 0.0001) were amongst some of the top correlative genes with AREG in the TCGA ovarian cancer cohort, adding a further degree of clinical relevance to our NanoString analysis." (PMID 38831884, 2024). "Importantly, it was previously shown that AREG-stimulated cell migration and proliferation were largely blocked by the addition of the metalloprotease inhibitor GM6001 to prevent the processing of membrane-bound AREG precursors into soluble AREG in ovarian cancers." (PMID 38727313, 2024). "The current study developed a predictive model of CSOARG for prognosis in ovarian cancer using eight key genes (WNK1, ANGPTL4, AREG, IGF1, CXCL10, GMPR, FANCB, LYG1)." (PMID 40510161, 2025). "The therapeutic potential of targeting YAP/TAZ and related signaling molecules such as Wnt5A, ET-1, AREG, and ECM components offers promising avenues for improving outcomes in ovarian cancer patients." (PMID 40630468, 2025). "To gain insight into the functional activity of ADAM17, we selected Nectin-4, HB-EGF and AREG as surrogate markers for ADAM17 activity and evaluated them as potential tumor markers for ovarian cancer." (PMID 36497350, 2022). "In contrast to ATF3, the role of Amphiregulin (AREG), which is a low affinity ligand for epidermal growth factor receptor (EGFR), has been more established in ovarian cancer." (PMID 36131935, 2022). "In particular, the ADAM17 substrates AREG and TGF-alpha were found in the ascites of ovarian cancer patients, suggesting high activity of ADAM17 in this tumor." (PMID 36140519, 2022).
ovarian carcinoma (continued). "It was shown that Nectin-4, HB-EGF, and AREG are proteolytically cleaved by the metalloprotease ADAM17 and represent essential factors in the regulation of ovarian cancer." (PMID 36497350, 2022). "A disintegrin and metalloprotease 17 (ADAM17) is highly expressed in ovarian cancer and required for releasing epidermal growth factor receptor (EGFR) ligands like amphiregulin (AREG)." (PMID 29662625, 2018). "In breast and ovarian cancers, SULF1 exhibition of a tumor suppressive effect was relevant to its ability to attenuate FGF2, HB-EGF, and amphiregulin signaling." (PMID 28525382, 2017). "Amphiregulin (AREG), the most abundant EGFR ligand in ovarian cancer, binds exclusively to EGFR and stimulates ovarian cancer cell invasion by down-regulating E-cadherin expression." (PMID 27835572, 2016). "AREG is a secreted glycoprotein and low-affinity epidermal growth factor receptor (EGFR) ligand and has an established role in promoting ovarian cell proliferation, metastasis, cancer stemness, and therapy resistance in ovarian cancer." (PMID 38831884, 2024). "Since AREG has not been previously studied as a biomarker for ovarian cancer, its predictive and prognostic potential were investigated in this publication." (PMID 36497350, 2022). "In addition, a monoclonal antibody blocking ADAM17 activity inhibited shedding of the ADAM17 substrates TNF, TNFR1-alpha, TGF-alpha, AREG, HB-EGF and IL-6Ralpha and reduced tumor growth, in an ovarian cancer xenograft model." (PMID 36140519, 2022). "Besides, a variety of ADAM17 substrates including the EGFR-ligands AREG and TGF-α were detected in patient-derived ascites of ovarian cancer patients, suggesting that ADAM17 is highly active in these patients." (PMID 29662625, 2018). "Previous studies have shown that AREG expression levels are significantly higher than EGF and TGF-α levels in ovarian cancer cells, tumor tissues and peritoneal and ascites fluid from patients with ovarian cancer." (PMID 27835572, 2016). "Given the evidence that AREG plays more important roles than EGF in the regulation of ovarian cancer progression, it is interesting and important to examine whether SPRY2 can be regulated by AREG and whether SPRY2 also affects the biological functions of AREG." (PMID 27835572, 2016). "The development of combinational therapies incorporating AREG inhibitors holds great promise for remodeling the TME and enhancing therapeutic outcomes in various cancer types, including colorectal cancer, pancreatic cancer, head and neck cancer, ovarian cancer, and lung cancer." (PMID 40725192, 2025). "Interestingly, cisplatin treatment increases AREG promoter activity but not EGF or TGF-α promoter activity, suggesting a possible role of AREG in regulating chemoresistance in ovarian cancer." (PMID 27835572, 2016).